CRP (C-reactive protein)
Diseases named in the same sentence as CRP in open-access papers (continued):
Sharing a sentence is not in itself a finding about the gene and the disease.
tumor (continued). "The 16-biomarker panels were divided into three categories of inflammatory markers (SAA, CRP, NLR, PLR, and LDH), TH1/TH2 cytokines (IL-2, IL-4, IL-5, IL-6, IL-8, IL-10, IFNγ, TNF, and GM-CSF), and HCC tumor markers (AFP and PIVKA-II)." (PMID 38409200, 2024). "Another study looking at blood biomarkers with an impact on GBM biology found that leucine-rich alpha-2-glycoprotein (LRG1), C-reactive protein (CRP), and complement component C9 (C9) were correlated with tumor size." (PMID 39057054, 2024). "These TMAs consisted of patients with tumors ≥7 cm, and patients were matched on age at the time of surgery, gender, performance status, preoperative serum CRP, NLR, pathologic stage, tumor size, grade, and the presence of tumor thrombus." (PMID 38339231, 2024). "Research shows that frailty can lead to elevated levels of IL-6, C-reactive protein (CRP), and TNF-α in the tumor microenvironment." (PMID 39042180, 2024). "As the tumor immune microenvironment changes after ICI administration, markers like the neutrophil‐to‐lymphocyte ratio and CRP levels can predict the efficacy of the treatment." (PMID 39170944, 2024). "The patients showed several correlations between treatment parameters like tumor size, tumor fraction, administered activity dose, and measured levels of leukocytes and ALP, CRP, as well as CLL2." (PMID 39199602, 2024). "Markers of tumor burden and inflammation (LDH, CRP, IL-6, IL-10, TNF-α, ferritin, fibrinogen, D-dimer) were correlated with aph-PET and car-PET features." (PMID 38649972, 2024). "By 10 months after diagnosis, the tumor had increased rapidly in diameter to 8 cm, with blood tests showing: WBC, 6500 /μL; CRP, 1.01 mg/dL; neutrophils, 68.2%; and lymphocytes, 19.3%." (PMID 39158760, 2024). "Worsening of function of the affected kidney can occur, in particular when serum CRP or LDH levels rise greatly after cryoablation, as well as when the tumor is located at the renal hilum or the volume of ablated normal renal parenchyma is large." (PMID 38744807, 2024). "The current European Association of Urology (EAU) guidelines propose using the neutrophil–lymphocyte ratio (NLR), albumin, C-reactive protein (CRP), De Ritis ratio, renal function and fibrinogen as prognostic indicators of tumor progression." (PMID 39272712, 2024). "This study also included the assessment of C-reactive protein (CRP) as a marker of inflammation, as well as CA19-9 and CEA as complementary tumour markers." (PMID 39766111, 2024). "The LASSO multivariate analysis further demonstrated that SAA, CRP and NLR were predicting factors for tumor response." (PMID 38409200, 2024). "Most patients with a high CRP level had a poor survival rate, especially those patients with an MSS tumour." (PMID 39613865, 2024). "However, the role of CRP in tumor progression remains unknown." (PMID 39564003, 2024). "Additionally, as the tumor grows, tissue necrosis may occur, releasing cellular contents and triggering further inflammatory responses that activate the immune system and stimulate additional CRP production." (PMID 39687887, 2024). "In SA region, the expression of CRP (P = 0.048), gp-130 (P < 0.001), JAK2 (P = 0.004), and IL-6 (P = 0.001) was lower in tumor tissues compared with normal tissues, while the expression of IL-6R (P = 0.191) and STAT3 (P = 0.960) was comparable." (PMID 38881895, 2024). "The feature importance of the CatBoost model and the most important features were as follows (in order of importance): response to the first IAT, ICI, maximum tumor size, BCLC grade, local therapy, PLT, PT, INR, CRP, TKI, AST, and Cre." (PMID 38291256, 2024). "IL‐6 secreted from CRP‐stimulated HMDMs also induced STAT3 activation in both HMDMs and tumor cells." (PMID 39564003, 2024). "Immune modulators secreted by tumor cells, including TGF-β, IL-10, and CRP, impair lymphocyte action in systemic inflammation." (PMID 39459558, 2024).
tumor (continued). "The list of candidates selected by random survival forest included sum of longest target lesion diameters, number of target lesions, ALP level, CRP level, lymphocyte proportion in intratumoral stroma, CD8+ T‐cell infiltration in the tumor center, and TMB." (PMID 38924353, 2024). "We investigated a few markers of systemic inflammation, including ANC, ALC, APC, CRP, albumin, and derived scores, like mGPS, NLR and to examine their relation to TME markers, tumor markers and CMS." (PMID 38645565, 2024). "Next, we conducted a PFS-related analysis for HCC treated with the combination of lenvatinib and PD-1 inhibitor therapy, and univariate results showed tumor number, NLR, PLR, PNI, CRP, and PMI as potential predictors of PFS." (PMID 38698848, 2024). "In our cohort, LDH and CRP were significantly higher in LNM patients, which aligned with previous reports about high LDH and CRP values in an advanced tumor stage." (PMID 38421522, 2024). "Single-cell transcriptome analysis also showed the expression of IL-6, gp-130, CRP and JAK2 was lower in tumor tissues compared with normal tissues." (PMID 38881895, 2024). "Hence, the increase in CRP levels following IL-6 upregulation may not only represent a reaction to tumor progression but also signify tissue inflammation and damage, which could potentially function as a mechanism linking low mGNRI levels and unfavorable survival outcomes." (PMID 38839809, 2024). "C-reactive protein (CRP) can directly interact with components of the extracellular matrix (fibroblasts), which are constituents of the tumor stroma." (PMID 39199673, 2024). "The primary tumor grew to 4 cm in diameter by 9 months after diagnosis, and blood tests showed: WBC, 7700 /μL; CRP, 0.18 mg/dL; neutrophils, 65.3%; and lymphocytes, 22.3%." (PMID 39158760, 2024). "We assessed the levels of CXCL12 and CXCR4 in the sera of 49 OC patients, considering the clinicopathological characteristics and comparing them with classical tumor markers (SCC-Ag and CEA) and markers of inflammation—CRP." (PMID 38673838, 2024). "These factors, such as the activation of pro-inflammatory cytokines and elevated C-reactive protein (CRP) levels, along with a reduction in anti-inflammatory cytokines, can impair anti-tumor immunity and potentially influence the response to ICIs." (PMID 38077332, 2023). "Recently, a novel tumour marker and inflammation index (TMII) based on serum CEA and CRP has been reported." (PMID 37036321, 2023). "Serum concentrations of CXCL1, CXCR1, and the classical tumor marker (CEA) were measured using immunoenzyme assays, while CRP levels were assessed with the immunoturbidimetric method." (PMID 37509572, 2023). "CRP-MC (Trip) and CRE-NP (α-M) pretreatment or simultaneous administration significantly inhibited tumor growth, and CRP-MC (Trip) and CRE-NP (α-M) pretreatment achieved the strongest anti-tumor effect and completely controlled tumor progression." (PMID 36869341, 2023). "Laboratory testing showed that C-reactive protein (CRP), procalcitonin (PCT), erythrocyte sedimentation rate (ESR) and female tumor markers were normal." (PMID 37248444, 2023). "A systemic inflammation-based prognostic risk classification was created by combining mGPS values before CRT, and C-reactive protein (CRP) levels after CRT, to distinguish tumor-derived inflammation from CRT-induced inflammation." (PMID 37686634, 2023). "While preoperative CRP-levels may be heavily influenced by preoperative infections, patients who have both, elevated CRP and elevated fibrinogen levels may have more severe long-lasting and tumour-related inflammatory states, leading to higher FC-scores and worse survival outcomes." (PMID 37024555, 2023). "Additionally, elevated CRP is an independent poor prognostic serum marker in small cell lung cancer and also is a potential poor prognostic indicator for non-small cell lung cancer as it has been correlated with tumor size and staging, with values > 40 mg/L possibly predicting metastasis." (PMID 37873776, 2023).
tumor (continued). "CA 15-3, CRP, and LDH levels were positively correlated with ulceration, tumor size, histopathological grade, metastatic lymph node, and clinical staging." (PMID 36938312, 2023). "MUC16 showed significant co-expression with antigens (tumor-antigens & autoantigens) and acute phase reactants such as transglutaminases (TGM2), CEACAMs, C-Reactive Protein (CRP), and alkaline phosphatase (ALPP)." (PMID 36816942, 2023). "Our present study revealed that CXCL1 concentrations were significantly higher in CRC patients when compared to healthy controls, and were similar to those of the classical tumor biomarker CEA and the marker of inflammation CRP." (PMID 37509572, 2023). "Tumor cells are positive for serum amyloid A (SAA) and C-reactive protein (CRP) by immunohistochemistry." (PMID 37835484, 2023). "The results showed that the clinical indicators including tumor stage, histological grade, PLT, CRP, LMR, histological type, HGB, BMI, Ascites, and Age play a more important role in the survival prediction of OC patients." (PMID 36645174, 2023). "This activation of IL6 promotes the STAT3 signaling pathway and induces an acute phase inflammatory response within the tumor, which is manifested by the expression of SAA and CRP." (PMID 37835484, 2023). "ctHPV16 at presentation is driven by tumor volume measured mostly by N. CYFRA 21-1 and CRP are additional factors related to ctHPV16 prior to the treatment." (PMID 38040848, 2023). "In conclusion, our study developed and validated a dynamic nomogram including BCLC staging, treatment modality, tumour size, and three laboratory parameters (ɣ-GGT, AFP and CRP), to predict the occurrence of MVI in patients with unresectable HCC." (PMID 35399712, 2022). "According to the variables of multiple factors, the indicators included in nomogram are BCLC staging, treatment, tumour size, ɣ-GGT, AFP and CRP." (PMID 35399712, 2022). "Elevated serum C-reactive protein (CRP) level is one of the most established markers of systemic inflammation, potentially affecting tumor immune-microenvironmental status." (PMID 36428750, 2022). "Third, adding tumour M2-PK to ESR and CRP increased the AUC of the ROC curve for differentiating RA with moderate/high from RA with remission/low disease activity to 0.962." (PMID 36059477, 2022). "It is worth noting that our CRC patients’ serum CRP and neutrophil-to-lymphocyte ratio (NRL) levels indicated that they were still in an inflammatory status after tumor resection." (PMID 36076975, 2022). "CRP and albumin-to-globulin ratio (AGR) significantly correlated with maximal tumor dimension and thiol group levels." (PMID 35629255, 2022). "A combination of inflammation biomarkers (CRP and NLR) can be used as a predictor of tumor response and survival." (PMID 35157721, 2022). "For example, the Glasgow score evaluating C-reactive protein (CRP) and albumin (Alb) projects prognostic performance among tumor cases." (PMID 36497225, 2022). "The prognostic and predictive value of CRP as a single pre-treatment measurement and as a longitudinal metric during ICI has been demonstrated for other tumor types." (PMID 36497270, 2022). "Using the ZJ cohort with a larger sample size, we further constructed a nomogram with clinical parameters of T stage, N stage, tumor differentiation, and preoperative NMPR, CRP and CEA levels." (PMID 36557010, 2022). "Age, sex, tumor location, hemoglobin, ASA score, C-reactive protein, ECOG score, LCR, and NRS2002 were identified as potential preoperative risk factors for AL in research." (PMID 35870933, 2022). "FC correlated positively with tumor stage (UICC based on WHO TNM classification) (rs 0.24; p = 0.007) and with CRP levels (rs 0.31, p = 001), and a negatively with B-haemoglobin (rs -0.21; p = 0.019)." (PMID 35331198, 2022).
tumor (continued). "The Munich-TACE score (M-TACE) uses the values of bilirubin, international normalized ratio, C-reactive protein, creatinine, and AFP, as well as tumor extension (size and number of nodules, vascular invasion, metastasis) to divide patients in three subgroups." (PMID 35330436, 2022). "The independent predictors including NMPR, CRP, CEA, T stage, N stage and tumor differentiation were used to establish nomogram." (PMID 36557010, 2022). "The comparison was made after the matching, in the age, gender, body mass index (BMI), preoperative C-reactive protein (CRP), carcino-embryonic antigen (CEA), tumor diameter, and tumor-node-metastasis (TNM) staging of patients." (PMID 35535225, 2022). "Among variables influencing survival, TNM stage, nodal involvement, tumour site, levels of CEA and CRP were confirmed." (PMID 35740504, 2022). "Area under the receiver operating characteristic curve (AUROC) analysis demonstrated that upon incorporation of tumour M2-PK, ESR, and CRP, the area under the curve was 0.962 for distinguishing moderate/high from remission/low disease activity." (PMID 36059477, 2022). "In the univariate analysis for survival in all DM patients, nodal involvement (N2 stage) (p = 0.020), tumour location (p = 0.050), level of CEA (p = 0.019), CRP (p < 0.001) and CLR (p = 0.001) were significantly associated with OS." (PMID 35740504, 2022). "We conducted a multivariable Cox regression analysis of PFS considering age (< 60/ ≥ 60), KPS (< 90/ ≥ 90), tumor size (< 4 cm/ ≥ 4 cm), extent of resection (GTR/STR), and baseline CRP (< 3.14/ ≥ 3.14)." (PMID 34882287, 2022). "The observed value is higher than SE of commonly used tumor markers such as CEA (75%), CA 19-9 (51%) and C-reactive protein (73%)." (PMID 35407400, 2022). "After matching, the age, gender, BMI, CRP, CEA, tumor diameter, and TNM staging of patients in the two groups were compared." (PMID 35535225, 2022). "Patients were divided into moderate/high disease activity (n=75) and remission/low disease activity (n=76) groups to evaluate the performance of tumour M2-PK, ESR, and CRP in differentiating disease status." (PMID 36059477, 2022). "Among variables influencing survival, TNM stage, nodal involvement, tumour site, levels of CEA and CRP were confirmed, with CRP level being the strongest one." (PMID 35740504, 2022). "CRP and albumin-to-globulin ratio (AGR) significantly correlated with thiols group level and maximal tumor dimension (p < 0.05)." (PMID 35629255, 2022). "We have also compared the obtained results to comparative, routinely used tumor markers (CA 19-9, CEA) and CRP (C-reactive protein), which is an inflammatory parameter." (PMID 35407400, 2022). "In contrast, CCL4 positively correlated with routine markers (CEA, CA 19-9), CRP protein, age (similar to CEA), and tumor stage (similar to CEA and CA 19-9)." (PMID 35407400, 2022). "They noted that the high-sensitivity inflammation-based prognostic index, a composite of CRP and WCC, was increased in patients with high grade tumours and was predictive of prognosis, further lending support for the prognostic role of inflammation in NECs." (PMID 34439386, 2021). "In the multivariate linear regression model, the variables that influence the mean CRP value in CRC patients included: WHO grade and tumor localization." (PMID 34441316, 2021). "In the multivariate linear regression model, the variables that influenced the mean CRP value in CRC patients included: WHO grade and tumor localization." (PMID 34441316, 2021). "Among factors influencing CRP concentration in CRC patients, we found: PLT, CA 19-9, WHO grade, TNM stage, and tumor location." (PMID 34441316, 2021). "Accordingly, a variable that combined tumor site and metastatic status was built, and each model included a term for the interaction between G8 on one hand and GPS, mGPS, CRP, albumin, and CRP/albumin ratio on the other." (PMID 34944774, 2021).
tumor (continued). "In the current study, we investigated the clinical significance of tumor expressions of HIF1A, VEGFA, CA9, and SLC2A1 assessed by IHC and markers of systemic inflammation (NLR and CRP) in pediatric patients with MPNST." (PMID 33810575, 2021). "In the AFP<100 IU/mL group, GGTP terciles showed differences in the tumor characteristics, with significantly more tumor multifocality and percent of patients with PVT in the high CRP group compared to the low CRP group." (PMID 34540270, 2021). "Linear regression analysis showed that among all proteins analyzed, only CRP was related to the WHO grade, TNM stage, and, likewise, tumor location." (PMID 34441316, 2021). "Patients with AAPR<0.50 had a significantly lower BMI, significantly larger tumor size, significantly higher NLR and CRP, and a significantly higher proportion of perineural and neural invasion than patients with AAPR≥0.50." (PMID 34746006, 2021). "The diagnostic accuracy (ACC) of CXCL8 (77%) was higher than CXCR2 (70%) and classical tumor markers, CEA (48%) and CA19-9 (66%), but lower than for CRP (79%)." (PMID 34680333, 2021). "Univariate analysis revealed that C-reactive protein (CRP)/mean corpuscular volume (MCV) ratio, TNM stage, differentiation, right-sided tumor, age, carcinoembryonic antigen (CEA) level, and CRP level were significantly associated with poor prognosis in CRC." (PMID 34221966, 2021). "There was a trend toward higher CRP levels in larger tumors (r = 0.5036; p = 0.009, q = 0.087, Spearman’s rho), whereas NLR levels were unrelated to tumor size." (PMID 33810575, 2021). "Thus, in conditions of high systemic CRP, there may be a greater likelihood of tumor cells undergoing an ‘immunologically silent’ death with minimal antigen presentation to facilitate priming and activation of effector T cells and may contribute to the lack of efficacy of a PD-L1 blockade." (PMID 33534859, 2021). "A panel of biomarkers (CA 125, CYFRA 21-1, HER2 shed antigen, LDH, and CRP) in combination with CEA and CA 15-3 has been shown to increase the sensitivity of early detection of asymptomatic tumor recurrence in BC patients." (PMID 34257557, 2021). "The lymphocyte to C-reactive protein (CRP) ratio (LCR) is an indicator of systemic inflammation and host–tumor cell interactions." (PMID 34229704, 2021). "Among factors influencing the CRP concentration, we found PLT, CA 19-9, WHO grade, TNM stage, tumor size, and location." (PMID 34441316, 2021). "According to our knowledge, the present study is the first that compares the diagnostic characteristics of all eotaxins and their receptor with the well-established tumor markers (CEA and CA 19-9) and the marker of inflammation (CRP) in CRC patients." (PMID 34204490, 2021). "SP for CCR3 (62.07%) was comparable to results of both tumor markers (CA 19-9 and CEA) but lower than SP observed for CRP (79.31%)." (PMID 34204490, 2021). "We also measured the commonly used tumor markers (CEA, CA 19-9) and C-reactive protein concentrations in CRC patients and in the control group." (PMID 34204490, 2021). "Serum CXCL8 and CXCR2 concentrations were significantly higher in GC patients than in healthy controls, similar to the well-established tumor marker (CA19-9) and marker of inflammation (CRP)." (PMID 34680333, 2021). "Inflammatory findings such as C reactive protein (CRP) and tumour makers were within the normal range (normal CRP, < 0.3 mg/dL)." (PMID 33926544, 2021). "The AUC for CXCL8 (0.8552, p < 0.001) was higher than the AUC for its receptor CXCR2 (AUC = 0.7773, p < 0.001) and classical tumor markers (CEA—AUC = 0.5159 and CA19-9—AUC = 0.6606), and also higher than the AUC for CRP levels (AUC = 0.8488, p < 0.001)." (PMID 34680333, 2021). "It decreased levels of the tumor (CEA and CA 19-9) and inflammatory (CRP and MPO) markers to normal levels in both of nano-extract simult- and post-treated groups." (PMID 34711004, 2021).